ACTBP11 (ACTB pseudogene 11)
Gene: Processed pseudogene on chromosome 1 (223,863,726 to 223,864,851, reverse strand). Ensembl gene ENSG00000188460.
Diseases named in the same sentence as ACTBP11 in open-access papers:
ACTBP11 is named in the same sentence as 1 disease in open-access papers, as found by Europe PMC text mining. Sharing a sentence is not in itself a finding about the gene and the disease. The quoted sentences say what the papers report.
breast carcinoma (1 paper, 2023). "For example, the pseudogene KRT8P32 has been identified in breast cancer and the pseudogene ACTBP11 was observed in GM12878 (B cells) cell lines according to Diana-LncBase V3." (PMID 37775701, 2023).